Y_RNA (Y RNA )
Gene: Miscellaneous RNA gene on chromosome 10 (92,710,499 to 92,710,608, reverse strand). Ensembl gene ENSG00000201412.
Homologues: Orthologues: chimpanzee Y_RNA (99% identical), macaque Y_RNA (95% identical). Paralogues in human: Y_RNA (89% identical), RNY1P5 (88% identical), Y_RNA (88% identical), Y_RNA (86% identical), Y_RNA (85% identical), Y_RNA (84% identical), Y_RNA (83% identical), Y_RNA (82% identical), RNY1 (81% identical), RNY1P1 (81% identical), RNY1P6 (81% identical), Y_RNA (81% identical), and 98 more.